LINC01503 (long independently transcribed non-coding RNA 1503)
Synonyms: lnc-PPP2R4-5; RP11-65J3.1
Gene: Long non-coding RNA gene on chromosome 9 (129,320,968 to 129,359,549, forward strand). Ensembl gene ENSG00000233901.
Diseases named in the same sentence as LINC01503 in open-access papers:
LINC01503 is named in the same sentence as 20 diseases in open-access papers, as found by Europe PMC text mining. Sharing a sentence is not in itself a finding about the gene and the disease. The quoted sentences say what the papers report.
gastric cancer (8 papers, 2021 to 2025). A primary or metastatic malignant neoplasm involving the stomach. "LINC01503 is involved in a variety of malignancies, including hepatocellular carcinoma, cholangio-carcinoma, non-small-cell lung cancer, cervical cancer, and gastric cancer." (PMID 36457749, 2022). "EGR1 has been reported to promote gastric cancer cell cycle progression and tumorigenesis through the mediated linc01503." (PMID 35223996, 2022). "LINC01503 acts as a carcinogen in cancers such as lung cancer, bowel cancer, and gastric cancer, and promotes tumor progression." (PMID 34712660, 2021). "Linc01503 was previously elucidated to promote gastric cancer (GC) cell invasion." (PMID 33145887, 2021). "In gastric cancer, EGR1 promoted the transcription of linc01503 and further affected the cell cycle." (PMID 36932397, 2023).
esophageal squamous cell carcinoma (4 papers, 2020 to 2021). Esophageal squamous cell carcinoma (ESCC) is a type of esophageal carcinoma (EC) that can affect any part of the esophagus, but is usually located in the upper or middle third. "For example, SE‐associated LncRNA LINC01503 was recently reported to promote the oncogenic phenotype of esophageal squamous cell carcinoma (ESCC) cells and was further identified as a squamous cell carcinoma‐specific lncRNA." (PMID 32460441, 2020). "LINC01503 has been reported as an oncogene in glioma, esophageal squamous cell carcinoma and colorectal cancer." (PMID 32432654, 2020). "LINC01503 is also overexpressed and plays oncogenic roles in esophageal squamous cell carcinoma." (PMID 32432654, 2020). "Up-regulated LINC01503 contributes to cell proliferation, growth, invasion, and migration in esophageal squamous cell carcinoma (ESCC), which may be used as a marker of aggressive ESCC." (PMID 32117736, 2020).
cholangiocarcinoma (3 papers, 2020 to 2023). A carcinoma that arises from the intrahepatic biliary tree (intrahepatic cholangiocarcinoma) or from the junction, or adjacent to the junction, of the right and left hepatic ducts (hilar cholangiocarcinoma). "Several studies subsequently reported that LINC01503 was overexpressed and could promote tumorigenesis and progression in colorectal cancer, glioma, and cholangiocarcinoma." (PMID 32661324, 2020).
colorectal cancer (3 papers, 2020). A primary or metastatic malignant neoplasm that affects the colon or rectum. "In addition, LINC01503 facilitates cell proliferation and invasion in colorectal cancer through targeting miR-4492/FOXK1 axis." (PMID 32432654, 2020). "Overexpressed LINC01503 regulates forkhead box K1 (FOXK1) expression by competing with miR-4492, which promotes cell proliferation and invasion in colorectal cancer." (PMID 32117736, 2020).
glioma (3 papers, 2020 to 2023). A benign or malignant brain and spinal cord tumor that arises from glial cells (astrocytes, oligodendrocytes, ependymal cells). "Recently, LINC01503 has been reported to promote tumorigenesis and progression of glioma by activating Wnt/β-catenin signaling." (PMID 32432654, 2020).
squamous cell carcinoma (3 papers, 2020 to 2021). A carcinoma arising from squamous epithelial cells. "For example, TP63 binding to the SE regions of lncRNA LINC01503 led to LINC01503 overexpression in squamous cell cancer." (PMID 33045741, 2021).
cervical cancer (2 papers, 2021 to 2022). A primary or metastatic malignant neoplasm involving the cervix. "High LINC01503 expression was associated with enhanced progression of cervical cancer as indicated by advanced FIGO stage, increased metastasis of tumor cells to lymph nodes, and invasion into deeper cervical tissues." (PMID 34149919, 2021). "Mechanistically, LINC01503 was demonstrated to negatively modulate the expression of miR-615-3p in cervical cancer." (PMID 34149919, 2021). "Here, we found higher levels of LINC01503 in cervical cancer tissues." (PMID 34149919, 2021).
hepatocellular carcinoma (2 papers, 2022 to 2023). A malignant tumor that arises from hepatocytes. "For example, SEs-associated lncRNAs such as LINC01503 in squamous cell carcinoma (SCC), lncRNA HCCL5 in Hepatocellular carcinoma (HCC), lncRNA UCA1 in Epithelial Ovarian Cancer, have been revealed in cancer." (PMID 37385987, 2023).
lung carcinoma (2 papers, 2021 to 2022). "LINC01503 is downregulated by c-Myc silencing to induce apoptosis of lung cancer cells, suggesting that c-Myc may upregulate LINC01503 to inhibit the apoptosis of lung cancer cells." (PMID 36230902, 2022).
non-small cell lung carcinoma (2 papers, 2022 to 2023). A group of at least three distinct histological types of lung cancer, including non-small cell squamous cell carcinoma, adenocarcinoma, and large cell carcinoma. "In non-small cell lung cancer samples, the expression of SE-lncRNA LINC01503 and LIM and SH3 domain protein 1 (LASP1) was increased, while the expression of miR-342-3p was downregulated, suggesting that SE-lncRNA LINC01503 may competitively bind LASP1 with miR-342-3p." (PMID 37501079, 2023).
gastric tumor (1 paper, 2020). "Moreover, LINC01503 can promote proliferation and metastasis in gastric tumor cells through the WNT signaling pathway." (PMID 33149738, 2020).
head and neck squamous cell carcinoma (1 paper, 2023). A squamous cell carcinoma that arises from any of the following anatomic sites: lip and oral cavity, nasal cavity, paranasal sinuses, pharynx, larynx, and salivary glands. "The transcription factor TP63 binds to the SEs region where LINC01503 is located to enhance its transcription and facilitate the invasion and metastasis of head and neck squamous cell carcinoma." (PMID 37658588, 2023).
liver cancer (1 paper, 2020). An epithelial or non-epithelial malignant neoplasm that arises from the liver. "Besides, LINC01503 promoted tumor growth of nude mice transplanted with liver cancer cells." (PMID 32547318, 2020).
tumor (14 papers, 2020 to 2025). "On the other hand, overexpressing LINP1 and EGOT and silencing BREA2 and LINC01503 significantly reduced the sensitivity of tumor cells to T-DM1 and increased their ability to invade and increase their colony formation capacity." (PMID 40925917, 2025). "In the current study, we demonstrated that elevated LINC01503 expression in CRC tumor tissues was relevant to tumor progression, vascular invasion, clinical stage, and poor prognosis." (PMID 39433507, 2024). "The involvement of LINC01503 in multiple biological processes has been reported in other tumor types." (PMID 33714257, 2021). "The bioinformatics analysis showed that linc01503 displayed remarkable upregulation in GC tissues compared with non‐tumour tissue samples." (PMID 33145887, 2021). "Firstly, bioinformatics analysis predicted a significantly altered expression of linc01503 between GC tissues and non‐tumour tissues." (PMID 33145887, 2021). "The role of linc01503 was detected by in vitro functional assays and in vivo xenograft tumour models." (PMID 33145887, 2021). "Collectively, these data suggest that LINC01503 promotes NPC tumor growth and lung metastasis in vivo." (PMID 32661324, 2020). "In our experiments, qRT-PCR analysis revealed that the expression of LINC01503 in tumor samples was markedly elevated in contrast to those in the corresponding normal samples." (PMID 32938459, 2020). "Collectively, these results indicate that high expression of LINC01503 in CRC tissues may promote disease progression and is associated with tumor angiogenesis." (PMID 39433507, 2024). "Consistently, linc01503 was dramatically increased in GC tissues relative to non‐tumour specimens." (PMID 33145887, 2021). "Knockdown of LINC01503 significantly delayed the tumor growth." (PMID 32661324, 2020). "We noticed that miR-342-3p, a tumor suppressor microRNA, was predicted to interact with LINC01503." (PMID 32938459, 2020). "Moreover, the LINC01503 expression correlated closely with high grade, high stage, large tumor size (T classification), as well as low overall survival rate in HCC patients." (PMID 32547318, 2020). "Targeted silencing of LINC01503 not only reduced the expression of VEGFA in CRC cells, but it also significantly inhibited tumor growth and metastasis of transplanted tumors in nude mice." (PMID 39433507, 2024). "Results revealed that LINC01503 expression was notably up-regulated and expression levels of NR2F1-AS1 and RNF217-AS1 were markedly down-regulated in TCGA STAD tumor tissues (n = 26) compared to the normal tissue group (n = 26)." (PMID 39007996, 2024). "Using bioinformatics analysis, we concluded that LINC01503 is an autophagy-related prognostic predictor for CRC, but further research is needed to investigate the mechanism by which LINC01503 regulates tumor biological behaviors via autophagy pathways." (PMID 34692467, 2021). "To determine the role of LINC01503 in NPC growth and metastasis in vivo, we firstly constructed a tumor growth model by injecting HK1 cells stably expressing shLINC01503 or its scramble control into the dorsal flank of nude mice." (PMID 32661324, 2020). "Interestingly, our findings indicate that the lncRNAs LINP1 and EGOT are released from tumor cells, whereas BREA2 and LINC01503 primarily originate from the exosomes of immune cells." (PMID 40925917, 2025). "Notably, silencing LINC01503 significantly reduced the expression levels of PCNA and CD31+ MVD in tumor tissues." (PMID 39433507, 2024).
cancer (9 papers, 2020 to 2024). A tumor composed of atypical neoplastic, often pleomorphic cells that invade other tissues. "LINC01503 is an oncogene, which has been closely associated with the malignant biological processes of many cancers." (PMID 39318250, 2024). "The dysregulation of linc01503 has been shown to strongly associate with advanced clinicopathological factors and foretell an unfavorable prognosis, indicating its prospective clinical significance as a valuable biomarker and therapeutic target for individuals with cancer." (PMID 38847945, 2024). "LINC01503, NR2F1-AS1, and RNF217-AS1 have been found to be implicated in the pathogenesis of multiple cancers including SC." (PMID 39007996, 2024). "In addition, LINC01503 has also been proved to play oncogenic roles in several cancer types, including colorectal cancer, glioma, and cholangiocarcinoma 9-11." (PMID 32547318, 2020). "LncRNA LINC01503 has been reported as an oncogene in several cancers." (PMID 32432654, 2020). "Mechanistically, LINC01503 accelerated proliferation and prohibited the apoptosis process via the MAPK (mitogen-activated protein kinase) / ERK (extracellular signal-regulated kinase) pathway, a crucial pathway for human cancer 12-14." (PMID 32547318, 2020).
LINC01503 also shares sentences with these, for which no sentence is quoted: adenocarcinoma (1 paper); bladder cancer (1); bowel cancer (1); nasopharyngeal carcinoma (1); ovarian serous cystadenocarcinoma (1).